ENSG00000252427
Synonyms: LOC124900314
Gene: Small nucleolar RNA gene on chromosome 11 (46,758,766 to 46,758,873, reverse strand). Ensembl gene ENSG00000252427.
Gene Ontology:
Biological process: RNA processing
Cellular component: nucleolus
Homologues: Paralogues in human: SNORD67 (63% identical).